TNF (tumor necrosis factor)
Diseases named in the same sentence as TNF in open-access papers (continued):
Sharing a sentence is not in itself a finding about the gene and the disease.
inflammatory bowel disease (continued). "Previous studies indicate that LAYN is involved in the tumor necrosis factor-α (TNF-α) induced epithelial-mesenchymal transition (EMT) of renal tubular epithelial cells as well as plays a critical role in HA35-induced intestinal epithelial tight junctions in inflammatory bowel disease." (PMID 30761122, 2019). "One example is to use NPs composed of poly(lactic acid)-poly(ethylene glycol) block copolymer (PLA-PEG) to deliver a TNF-α siRNA to M1 macrophages in the model of inflammatory bowel disease (IBD)." (PMID 31497026, 2019). "For example, whereas corticosteroids used for treatment of inflammatory bowel disease have well-documented side-effects resulting in impaired glucose regulation, biologicals such as tumor necrosis factor-α antagonists may alleviate inflammation and therefore potentially improve glucose regulation." (PMID 30373718, 2018). "Anti-TNF antibodies are highly effective therapies for treating pediatric inflammatory bowel disease (IBD)." (PMID 30009157, 2018). "In inflammatory bowel disease (IBD), IL-34 protects the integrity of the intestinal epithelium, and IL-34-differentiated macrophages show decreased IL-1β and TNF-α expression." (PMID 30405534, 2018). "H and mH suppressed the production of the inflammatory mediators nitric oxide (NO), interleukin (IL)-6, IL-8, and tumor-necrosis factor (TNF)-α, which are most highly activated in inflammatory bowel disease (IBD)." (PMID 29673161, 2018). "Tumour necrosis factor [TNF] antagonists have revolutionised the treatment of inflammatory bowel disease [IBD]." (PMID 29788248, 2018). "Patients with inflammatory bowel disease (IBD) are at increased risk for developing opportunistic infections due to factors that include receiving immunosuppressive and immunomodulatory therapy [particularly anti-tumor necrosis factor-α (anti-TNF-α) agents], severity of disease, and malnutrition." (PMID 30514241, 2018). "The study showed that LPS was identified by Toll like receptor 4 (TLR4) to release TNF-α, IL-1 beta and IL-6 and other cytokines, which mediate and promote the occurrence of inflammatory bowel disease (IBD)." (PMID 30075775, 2018). "Inflammatory bowel diseases (IBD) are chronic disorders of the gastro-intestinal tract where TNFα is a key cytokine." (PMID 32232080, 2018). "Anti-TNF therapy is the mainstay for the treatment of moderate-to-severe inflammatory bowel disease (IBD), including Crohn’s disease (CD) and ulcerative colitis (UC)." (PMID 30558178, 2018). "Therapeutic drug monitoring (TDM) aid therapeutic decision making in patients with inflammatory bowel disease (IBD) who lose response to anti-TNF therapy." (PMID 28789636, 2017). "With the increasing use of anti-TNF therapy in inflammatory bowel disease (IBD), a shift of costs has been observed with medication costs replacing hospitalization and surgery as major cost driver." (PMID 27099937, 2016). "The introduction of anti-tumor necrosis factor alpha (anti-TNF) antibodies to the treatment of inflammatory bowel diseases (IBD) is considered to be one of the most important advances in gastroenterologic therapeutics in recent years." (PMID 25993615, 2015). "Another study demonstrated that OSM inhibits LPS-induced TNF-α expression, which represents a key inflammatory cytokine in inflammatory bowel disease (IBD) and other chronic inflammatory diseases." (PMID 24710357, 2014). "Predictors of NL within the AS group included prior diagnosis of inflammatory bowel disease (IBD) (HR 2.3; 95%CI 1.7 to 3.3), prior diagnosis of NL (HR 16.4; 95%CI 11.5 to 23.4), and patients receiving anti-TNF treatment (HR 1.6; 95%CI 1.2 to 2.1)." (PMID 25423471, 2014).
inflammatory bowel disease (continued). "Antitumor necrosis factor (TNF) biologics appeared over a decade ago in the armamentarium for inflammatory bowel disease (IBD)." (PMID 24757282, 2014). "Locally elevated LITAF protein was reported in Crohn's disease (CD) and ulcerative colitis (UC), two major TNF-mediated inflammatory bowel diseases (IBD)." (PMID 23414097, 2013). "Tumor necrosis factor (TNF) is an important cytokine in the pathogenesis of inflammatory bowel disease (IBD)." (PMID 22937039, 2012). "In the present study, TNF-α and IFN-γ were used to simulate intestinal barrier dysfunction since they exhibit increased expression levels in patients with inflammatory bowel disease." (PMID 40568574, 2025). "Previous work demonstrated that patients with inflammatory bowel disease (IBD) who were treated with anti-TNF biologics exhibited decreased Spike-specific antibody responses compared with patients with IBD treated with anti-IL-12/23 or healthy controls, even after 4 doses of mRNA vaccine." (PMID 40728886, 2025). "In inflammatory bowel disease (IBD), for example, anti-TNF therapies are often administered via injection or intravenous delivery, which can lead to systemic side effects like increased infection risk." (PMID 40557148, 2025). "In a dextran sodium sulfate (DSS)-induced murine model of colitis, DSS treatment resulted in a significant increase in the expression levels of pro-inflammatory cytokines such as IL-1β, TNF-α, and IL-6, which play key roles in the pathogenesis of inflammatory bowel disease (IBD)." (PMID 40051564, 2025). "The Kyoto Encyclopedia of Genes and Genomes (KEGG) pathway was enriched mainly in the mTOR signaling pathway, TNF signaling pathway, Jak-STAT signaling pathway and inflammatory bowel disease." (PMID 39809743, 2025). "Enriched pathways included Inflammatory bowel disease, IL-17 signalling pathway, JAK-STAT signalling pathway, Neuroactive ligand-receptor interaction, NF-kB, TNF, HIF-1, cAMP, and MAPK signalling pathway." (PMID 40430430, 2025). "These genes were mainly involved in several signaling pathways, such as TNF signaling pathway, IL-17 signaling pathway, FOXO signaling pathway, inflammatory bowel disease." (PMID 40303487, 2025). "This is consistent with previous studies indicating that TNF-α enhances Th17 polarization, contributing to chronic inflammatory diseases such as T2DM, RA, and inflammatory bowel disease." (PMID 41030441, 2025). "As significant biologic therapeutics, tumor necrosis factor-alpha (TNF-α) inhibitors have achieved groundbreaking progress in treating pediatric chronic inflammatory diseases, including inflammatory bowel disease (IBD) and juvenile idiopathic arthritis (JIA)." (PMID 41329755, 2025). "In inflammatory bowel disease (IBD), this shift reduces colonic inflammation and promotes mucosal healing, as evidenced by decreased TNF-α and increased IL-10 levels in murine colitis models." (PMID 40809065, 2025). "In inflammatory bowel disease (IBD), M1-polarized macrophages primarily contribute to mucosal barrier disruption and increased pathogen invasion through TNF-α secretion." (PMID 41142308, 2025). "During the pathogenesis of inflammatory bowel disease (IBD), the formation of NETs can activate the production of various pro-inflammatory factors, such as IL-1β, TNF-α, and IL-17A." (PMID 40620701, 2025). "TNF-α inhibitors are well-established treatments for a range of severe immunoinflammatory diseases and have demonstrated substantial clinical benefit in conditions such as rheumatoid arthritis and inflammatory bowel disease (IBD)." (PMID 40481519, 2025). "TNFα inhibitors (TNFαI) are indicated for several inflammatory diseases in children, including psoriasis, hidradenitis suppurativa, uveitis, inflammatory bowel disease (IBD) and juvenile idiopathic arthritis (JIA)." (PMID 40481366, 2025).
inflammatory bowel disease (continued). "Infliximab, a monoclonal antibody targeting tumor necrosis factor-alpha (TNF-α), is widely used in treating inflammatory bowel diseases (IBD), including ulcerative colitis (UC)." (PMID 40144881, 2025). "Interferon-gamma (IFN-γ) and tumor necrosis factor-alpha (TNF-α), derived from T cells, are key mediators of intestinal inflammatory diseases, including inflammatory bowel disease (IBD)." (PMID 40370438, 2025). "Inflammatory bowel disease (IBD) and many other inflammatory disorders are characterized by elevated expression of pro-inflammatory cytokines, such as TNF-α, IL-6 and IL-1β." (PMID 40391223, 2025). "Here we describe a patient who developed inflammatory bowel disease (IBD) requiring treatment with infliximab, a chimeric monoclonal antibody against TNF-α around the time of developing T1D." (PMID 39252097, 2024). "Infliximab (IFX) is a chimeric monoclonal antibody that targets tumor necrosis factor alpha (TNF-α), a proinflammatory cytokine that plays a key role in the pathogenesis of inflammatory bowel disease (IBD)." (PMID 39594941, 2024). "Despite significant advancements in medical therapeutic approaches, such as corticosteroids, immunosuppressants and anti‐TNF‐α monoclonal antibodies (mAbs), existing therapies for inflammatory bowel disease (IBD) still face limitations in achieving satisfactory response and remission rates." (PMID 38533646, 2024). "Our findings suggest that resveratrol may exhibit anti-inflammatory effects in Inflammatory Bowel Disease (IBD) by increasing IL-10 levels and decreasing TNF-α, IL-6, IL-1β, and IL-8 levels." (PMID 38948464, 2024). "KEGG pathway enrichment analysis revealed that, aside from the inflammatory bowel disease (IBD) pathway, there was significant gene enrichment in the NOD-like receptor and TNF-α signaling pathways." (PMID 39766817, 2024). "In a cohort of patients with inflammatory arthritis or inflammatory bowel disease treated with TNFi, patients treated with CZP had the lowest concentrations of free TNF measured using a drug-tolerant ELISA." (PMID 39296891, 2024). "However, primary non-response has been observed in 10% to 40% of inflammatory bowel disease (IBD) patients treated with anti-TNF-α drugs." (PMID 39425179, 2024). "For patients with inflammatory bowel disease (IBD), TNF-α, IL-12/23, IL-23, or JAK inhibitors are recommended." (PMID 38029150, 2023). "For this reason, TNF-α inhibitors have been largely used throughout recent history for managing inflammatory diseases such as SpA, RA, psoriasis, inflammatory bowel disease IBD, and juvenile idiopathic arthritis." (PMID 37047435, 2023). "It has been shown that tumor necrosis factor-alpha (TNF-α), a key cytokine in the pathogenesis of inflammatory bowel disease, alters the tight junctions between epithelial cells." (PMID 37763228, 2023). "Compared with Group M, the down-regulated DEGs in Group H were not only enriched in the TNF, IL-17, TH17, HIF signaling pathways, but also involved in inflammatory bowel disease and Intestinal immune network for IgA production." (PMID 37960213, 2023). "Anti-TNF-α, particularly in the form of monoclonal antibodies, appears to be more effective, especially when patients have additional conditions like inflammatory bowel disease (IBD) or enthesitis-related arthritis." (PMID 38137947, 2023). "Tumor necrosis factor (TNF), a family of genes involved in inflammation, has strong pro‐inflammatory activity and is one of the key factors in inflammatory bowel disease, spondylitis and brain injury." (PMID 38680513, 2023). "In inflammatory bowel disease (IBD), TLR-4 in intestine induces a Th1 inflammatory response, producing the inflammatory cytokines IFN-γ and tumor necrosis factor (TNF), and then upregulating TLR-4, forming an “autocrine loop”." (PMID 38012694, 2023).
inflammatory bowel disease (continued). "Previous in vitro investigations had shown that both IL-6 and TNF were necessary to trigger TNFR2 in CRC cells, perhaps indicating a physiological microenvironment of several cytokines in inflammatory bowel disease (IBD) or IBD-associated CRC." (PMID 36672682, 2023). "CD is an idiopathic inflammatory bowel disease (IBD) whose pathophysiology shares certain features with the immune response to tuberculosis, such as the formation of granulomas in tissue and vulnerability to TNF blockade." (PMID 37922286, 2023). "It often coexists with other TNF-α-mediated immune-mediated diseases such as juvenile idiopathic arthritis (JIA) and inflammatory bowel diseases." (PMID 37325364, 2023). "In the cellular model of inflammatory bowel diseases, ATF6 increases expression of inflammatory cytokines CXCL1 and tumor necrosis factor (TNF) in response to ER stress." (PMID 38007457, 2023). "Application of tofacitinib, a drug approved for treatment of RA and inflammatory bowel disease (IBD), on TNF-α/IL-17A–triggered BMS astrocyte/NGN2-neuron cocultures resulted in the loss of BMS astrocytes’ ability to protect neurons against the TNF-α/IL-17A–induced neurite damage." (PMID 37219933, 2023). "In in vivo experiments in an inflammatory bowel disease model animal, EVs from primed IFN-γ and TNF-α MSCs were further able to induce M2 macrophage polarization and modulate T cells activation and the expression of cytokines in the colon." (PMID 37507751, 2023). "Several studies have demonstrated that patients with inflammatory bowel disease (IBD) undergoing anti-TNF therapy; combination therapy of anti-TNF and thiopurines; or tofacitinib exhibit a significantly impaired humoral immune response following the second SARS-CoV-2 vaccination." (PMID 37766088, 2023). "For example, to generate a porcine model for inflammatory bowel disease (IBD), two guide RNAs were designed to delete the adenosine–uracil-rich element (ARE) within the 3’ UTR region of the porcine TNF gene." (PMID 37886655, 2023). "In general, inflammatory bowel disease (IBD) patients exhibit an excessive immune response to commensal bacterial antigens, resulting in the release of pro-inflammatory cytokines, such as IL-1β, TNF-α, IL-6, and IL-12." (PMID 37376017, 2023). "Vedolizumab is indicated in patients with inflammatory bowel disease (IBD) who fail conventional therapy with immunosuppressants (including thiopurines and/or methotrexate) or anti-TNF agents." (PMID 36986833, 2023). "The core pathway related to UC was inflammatory bowel disease referring to IL6, TNF, RELA, and STAT3." (PMID 36382627, 2022). "Among these, the core pathway related to UC was inflammatory bowel disease (KEGG:05321), containing the hub targets of IL6, TNF, RELA, and STAT3." (PMID 36382627, 2022). "On protein level, the key proteins like IL-6, TNF-α, NFKBp65, and STAT3 of the inflammatory bowel disease pathway had the same change trend." (PMID 36382627, 2022). "Infliximab, a chimeric monoclonal antibody against anti-tumor necrosis factor-α (TNF-α), has revolutionized the management of inflammatory bowel disease." (PMID 36389693, 2022). "In a separate inflammatory bowel disease (IBD) murine model, OXTR knock-out mice displayed an increased number of pro-inflammatory cytokine transcripts encoding for TNF-α, IL-1β, and IL-6 and exhibited shorter villi and crypts in the intestinal mucosa, a sign of chronic inflammation." (PMID 38983562, 2022). "This review compares five publications with the use of a combination of biological agents (TNF antagonists, VDZ or US and tofacitinib) in pediatric inflammatory bowel disease." (PMID 35407612, 2022). "In the context of inflammatory bowel disease, CD8+γδ T cells have been shown to have cytotoxic potential, able to produce IFNγ and TNF, and correlate negatively with disease activity." (PMID 35922467, 2022).
inflammatory bowel disease (continued). "Resistance to single cytokine blockade, namely anti-tumor necrosis factor (TNF) therapy, is a growing concern for patients with inflammatory bowel disease (IBD)." (PMID 35660024, 2022). "CCL20 can be induced by pro-inflammatory signals such as TNF-α or TLR, bind CCR6 and induce the recruitment of B cells with high CCL6 expression into intestinal epithelial cells of patients with inflammatory bowel disease in response to inflammatory stimuli." (PMID 36419192, 2022). "Consistently, serum levels of eNAMPT were found to be elevated in inflammatory bowel disease (IBD) patients who showed resistance to anti-TNFα therapy, and eNAMPT neutralization, with an anti-eNAMPT monoclonal antibody, ameliorated acute and chronic colitis in experimental mice models." (PMID 34068917, 2021). "Numerous pieces of evidence estimate that in inflammatory bowel diseases (IBD), local TNF-α secretion induces not only tissue damage but also activation of the adaptive immune system, which perpetuates the inflammatory state resulting in systemic inflammation." (PMID 34829740, 2021). "Curcuma relieved the colon inflammation of ulcerative colitis via inactivating TNF pathway, inflammatory bowel disease pathway, and epithelial cell signaling in Helicobacter pylori infection pathway, probably by binding to STAT3 and TNF-α." (PMID 34221084, 2021). "Top 20 enriched pathways ranked by significance include TNF signalling pathway, JAK/STAT signalling pathway and NFκB signalling pathway, as well as inflammatory diseases, including inflammatory bowel disease." (PMID 34018320, 2021). "Interestingly, some late-onset IPEX patients had been initially treated as IBD (Inflammatory Bowel Disease) and some received anti-TNF therapy with low clinical response." (PMID 33614561, 2021). "Organoids derived from colonic biopsies of inflammatory bowel disease patients have also been derived, and showed an upregulation of the pro-inflammatory cytokines, MCP-1 and TNF-a." (PMID 34072095, 2021). "Several studies have estimated that approximately one-third of inflammatory bowel disease patients experience LOR and require DI, and that occurs more frequently in patients with prior anti-TNF exposure." (PMID 34069295, 2021). "Tumor necrosis factor-α (TNF-α) is a pleiotropic proinflammatory cytokine, which is involved in pathophysiology of inflammatory bowel disease (IBD) and present at high levels in serum and tissues of CRC patients." (PMID 33961948, 2021). "Furthermore, anti-TNF non-responders with inflammatory bowel disease had upregulated CCR2 expression, which might cause lower serum CCL2 levels than those seen in the responders." (PMID 34367126, 2021). "Inflammatory bowel disease (IBD) is commonly treated with corticosteroids and anti–tumor necrosis factor (TNF) drugs; however, medications have well-described adverse effects." (PMID 33646314, 2021). "A study of animal inflammatory bowel disease showed that most of the Th17 cells were found in the ileum and colon of mice, and the contents of Th17-related cytokines IFN-γ and TNF-α were significantly increased (Flavio, Francesco, and Giovanni, 2008)." (PMID 33981227, 2021). "Tumor necrosis factor-alpha (TNF-alpha) inhibitors such as adalimumab, infliximab and etanercept are commonly used in the treatment of pediatric inflammatory bowel disease." (PMID 34209280, 2021). "Regarding the antagonism of the two cytokines, studies have shown that in inflammatory bowel disease (IBD), TNF-α can inhibit the synthesis of IL-25, while TGF-β1 can stimulate the up-regulation of IL-25 in colon tissue." (PMID 35069596, 2021). "TNF-α includes the transmembrane type and secreted type, among which transmembrane type TNF plays a more important role in inflammatory bowel disease." (PMID 33553436, 2021). "Intestinal BD, similar to other inflammatory bowel diseases, such as CD and ulcerative colitis, is usually treated with 5-ASA, corticosteroids, immunomodulators, and/or anti-TNF agents." (PMID 34620099, 2021).